LINC02693 (long independently transcribed non-coding RNA 2693)
Synonyms: C17orf51; FLJ12977; FLJ31874; FLJ33618
Gene: Long non-coding RNA gene on chromosome 17 (21,428,263 to 21,574,517, reverse strand). Ensembl gene ENSG00000212719.
Diseases named in the same sentence as LINC02693 in open-access papers:
LINC02693 is named in the same sentence as 4 diseases in open-access papers, as found by Europe PMC text mining. Sharing a sentence is not in itself a finding about the gene and the disease. The quoted sentences say what the papers report.
herpes infection (1 paper, 2025). "Its involvement in paraspeckle formation could also be explored for broader antiviral strategies.LncRNAs, including LINC02693, C6orf223, TMEM132E-DT, and LINC02908, regulate gene expression, immune responses, and viral replication in herpes infection." (PMID 40144645, 2025).
cancer (1 paper, 2023). A tumor composed of atypical neoplastic, often pleomorphic cells that invade other tissues. "According to our study, in HCC, we extracted RCORs-miRNA-lncRNA pairs, such as RCOR1-hsa-miR-9-3p-CT62, RCOR2-hsa-miR-1343-3p-LINC02693, RCOR3-hsa-miR-128-3p, etc., offering potential targets for cancer therapy." (PMID 37342230, 2023).
LINC02693 also shares sentences with these, for which no sentence is quoted: Cirrhosis (1 paper); psoriasis (1).